RFX1 (regulatory factor X1)
Diseases named in the same sentence as RFX1 in open-access papers (continued):
Sharing a sentence is not in itself a finding about the gene and the disease.
cancer (18 papers, 2011 to 2025). A tumor composed of atypical neoplastic, often pleomorphic cells that invade other tissues. "Previously, high RFX1 expression has been elucidated to be significantly associated with poorer patient prognosis, including cancer progression and immune microenvironment." (PMID 41425715, 2025). "The RFX1 (regulatory factor X1) gene encodes a transcription factor involved in immune responses and cancer, including the regulation of MHC class II genes." (PMID 39589950, 2024). "Cancers with severe stages, grades, or subtypes associated with a poor prognosis, decreased survival and increased recurrence had decreased RFX1 expression." (PMID 33964962, 2021). "RFX1 encodes for a transcription factor that regulates a variety of genes involved in immunity and cancer, including the MHC class II genes." (PMID 29867904, 2018). "In summary, RFX1 is closely linked to immune modulation across cancers." (PMID 41425715, 2025). "In patients with HCC, downregulated RFX1 is correlated with poor prognosis and high recurrence risk, whereas RFX1 overexpression decreases cancer invasion and epithelial-mesenchymal transition 55, which plays a crucial role in the early stages of metastasis 56,57." (PMID 37781522, 2023). "Even though members of the RFX protein family such as RFX4-7 are linked to the formation or suppression of cancer, the broader regulatory role, defined activation and repression domains, and the unique mechanism of auto-repression make RFX1 an ideal candidate to be studied individually." (PMID 33964962, 2021). "RFX1-mediated tumor suppression can also be mediated by inducing cancer stem cell differentiation, thereby rendering cancer cells vulnerable to chemotherapy." (PMID 41425715, 2025). "Characterising the immune landscape of RFX1 in pan-cancer facilitates the profiling of potential anti-RFX1 immunotherapies or the targeting of specific tumor markers." (PMID 41425715, 2025). "We obtained 122 marker genes for immunomodulators, including chemokines, immunosuppressive factors, MHC, receptors, and other characterisation dimensions, and explored their relevance to RFX1 in pan-cancer." (PMID 41425715, 2025). "RFX1 has been identified as a potential therapeutic target for cancers due to its involvement in many processes that are thought to interfere with cancer stem cells." (PMID 40619810, 2025). "Our study provides evidence to suggest that thiazolidinediones and WY‐14643 can increase RFX1 expression to inhibit cancer cell behaviour, a novel mechanism for their anticancer effects." (PMID 39636301, 2024). "Silencing RFX1 attenuated hypoglycemic agent‐induced inhibition of cancer cell behaviours and MMP2 activity." (PMID 39636301, 2024). "In this review, we compile significant evidence for the tumor-suppressive activities of RFX1 while also analyzing its oncogenic potential in some cancers." (PMID 33964962, 2021). "RFX1, explicitly or implicitly, influence the significant pathways involved in cancer stemness, including Notch, Wnt, PIK3-AKT, and JNK/STAT." (PMID 33964962, 2021). "RFX1 potentiates c-Abl kinase activity, the role of which varies among different cancers and its subtypes." (PMID 33964962, 2021). "Tissue expression profiles from the GENT2 database exhibited a differential expression pattern of RFX1 in cancer tissues compared to normal tissues." (PMID 33964962, 2021). "From these observations, it is clear that the altered expression and cancer types are crucial in interpreting RFX1 mediated gene regulation." (PMID 33964962, 2021). "RFX1-mediated-tumor repression is also attained by inducing differentiation of cancer stem cells, thereby making cancer cells vulnerable to chemotherapy." (PMID 33964962, 2021). "The study revealed the down-regulation of RFX1 in cancer compared to healthy tissues as well as in patient samples." (PMID 33964962, 2021). "The reversal of RFX1 gene silencing at the epigenetic level is a promising strategy for treating cancers." (PMID 33964962, 2021).
cancer (continued). "Overexpression of RFX1 decreased cancer invasion with decreased EMT marker, vimentin, and an increase in E-cadherin." (PMID 33964962, 2021). "RFX1 expression was increased with methylation inhibitor 5- azacytidine, which reduced cancer cell proliferation." (PMID 33964962, 2021). "A significant reduction of RFX1 expression in breast, bone, lung, oesophagus, prostate, and in 11 other cancer tissues were observed." (PMID 33964962, 2021). "In cancer, RFX1 promotes differentiation of CSCs by directly and indirectly targeting major stemness regulators like c-Myc, FGF1, and CD44." (PMID 33964962, 2021). "For this, proper elucidation of the RFX1 interactome coupled with the identification of key signalling pathways and identification of post-translational modifications of RFX1 and effect on DNA binding in different cancer types is necessary." (PMID 33964962, 2021). "RFX1 can regulate a handful of proto-oncogenes as well as tumor suppressors, eventually regulating cancer hallmarks." (PMID 33964962, 2021). "D1 germ cell tumor cells, RFX1 down-regulated the promoter activity of MDR proteins involved in cancer stemness and drug resistance (unpublished results)." (PMID 33964962, 2021). "Though direct evidence on RFX1-mediated chemo-sensitization is limited, RFX1 targets are often involved in mediating drug resistance and cancer recurrence." (PMID 33964962, 2021). "RFX1 reduces cancer cell proliferation by targeting FGF1 and transforming growth factor beta 2 (TGFβ2), induce differentiation by targeting CD44 and c-Myc, and promote apoptosis by regulating myeloid cell leukemia sequence 1 protein (MCL1)." (PMID 33964962, 2021). "From the current literature, we draw together different RFX1 transcriptional factor regulation systems to highlight the importance of its induction for targeted cancer therapy." (PMID 33964962, 2021). "Targeting RFX1 is beneficial in many cancers as it counters the possible mechanisms of cancer cell survival and maintenance." (PMID 33964962, 2021). "RFX1 induction decreased cellular proliferation, modulated the immune system, induced apoptosis, reduced chemoresistance, and sensitized cancer stem cells for chemotherapy." (PMID 33964962, 2021). "The mammalian homolog of this gene, RFX-1, was shown to regulate several genes involved in immunity and cancer progression." (PMID 30209405, 2018). "It is shown that homologues of Crt1/Rfx1 which work as transcription repressors play an important role in for DNA damage induced transcription of R2 gene in yeast and mammalian cancer cells." (PMID 21887375, 2011). "Given the difficulties in qualitative assessment of tissue morphology, specific molecular markers such as Rfx1 can be of high utility in the diagnosis of cancer and its precursors." (PMID 21935353, 2011). "Many well-known cancer markers appear in a frequency comparable to or less than those in our initial studies of Rfx1." (PMID 21935353, 2011). "In an array of diverse cancer tissues, including those of the breast, bone, lung, esophagus, prostate, and an additional 11 tissues, a notable and statistically significant reduction in RFX1 expression was observed." (PMID 41425715, 2025). "Cancer tissues with poorer grades and types have a lower expression of RFX1." (PMID 39636301, 2024). "Finally, RFX1 reduces chemotherapy resistance and cancer recurrence by regulating the expression of genes, including multidrug resistance genes." (PMID 39636301, 2024). "First, cancer tissues have a lower expression of RFX1 than the adjacent non‐cancer tissues." (PMID 39636301, 2024). "The mechanisms for RFX1's anticancer effects may be through its regulation of the expression of many genes that are involved in tumour genesis and cancer cell biology." (PMID 39636301, 2024). "Thus, our review discusses the pleiotropic function of RFX1 in multitudinous gene regulations, decisive protein–protein interactions, and also its role in regulating key cell signaling events in cancer." (PMID 33964962, 2021).
cancer (continued). "Interventions targeted to regain proper regulation of RFX1 at epigenetic or transcriptional levels can have far-reaching outcomes and could be crucial in cancer treatment." (PMID 33964962, 2021). "The changes in RFX1 levels could play a significant role in attaining chemoresistance in cancer cells." (PMID 33964962, 2021). "Our review aims to discuss the possibility of RFX1 targeted therapy in suitable cancers." (PMID 33964962, 2021). "The induction of differentiation by RFX1, which helps in the inhibition of cancer stemness, is a promising therapeutic intervention and could prevent recurrence and resistance." (PMID 33964962, 2021). "Hence, both oncogenesis and tumor suppression events are to be discussed for evaluating the role of RFX1 in cancer." (PMID 33964962, 2021). "RFX1 was significantly down-regulated in HER2 positive cancer tissues compared to other subtypes and may aid in targeted therapy and Lapatinib sensitization." (PMID 33964962, 2021). "Prevailing pieces of evidence suggest that RFX1 is a transcription factor that regulates a wide array of genes, and a better understanding of it's role can deduce its clinical implications in diseases like cancer." (PMID 33964962, 2021). "RFX1 can play an anti-cancer role by down-regulating the original oncogene c-MYC." (PMID 32799626, 2020). "Thus, increasing RFX1 may be an effective approach to inhibit cancer cell behaviours, such as cell proliferation, migration and invasion." (PMID 39636301, 2024). "Some target genes of RFX1 are known to include MHC class II genes, which encode important antigen-presenting molecules in the immune system and participate in processes such as antibody-mediated immune responses, which is not only for cancer immune reaction but also for HPV immune reaction." (PMID 38235142, 2023). "RFX1 downregulated cancers may benefit from targeting uncontrolled autorepression of RFX1." (PMID 33964962, 2021). "Some key miRNAs and lncRNAs affecting RFX1 could be instrumental in its regulation in cancer." (PMID 33964962, 2021). "Notably, RFX1 tends to be a negative regulator of oncogene expression in most cancers." (PMID 33964962, 2021). "RFX1 can increase major histocompatibility complex(MHC) class II gene expression, key in antigen presentation and cancer cell apoptosis by effector immune cells." (PMID 33964962, 2021). "There are many ways by which Notch signaling gets activated in cancer cells, and one of the Notch inducers is FGF1, which RFX1 negatively regulates." (PMID 33964962, 2021). "On the other hand, several HBV inhibitors, for example, ONECUT1, RFX1, and SIRT1 appeared to be up-regulated in less differentiated cancer cells." (PMID 34290079, 2021). "It is advised to determine the presence/absence of RFX1 promoter hypermethylation in other cancers and its relation with methyltransferases." (PMID 33964962, 2021). "RFX1 can inhibit cell migration and invasion by repressing FGF1 in many cancers." (PMID 33964962, 2021). "This is especially relevant in the case of RFX1, as seen in HL60 cancer cells." (PMID 33964962, 2021). "RFX1 downregulates such pro-tumor factors like Toll-like receptor 4 (TLR4), Interleukin 17A (IL17A), interleukin 5 receptor subunit alpha (IL5RA), and helps in cancer mitigation while being anti-inflammatory." (PMID 33964962, 2021). "The downregulation of RFX1 has been shown to predict poor prognosis in patients with small hepatocellular carcinoma, while TFCP2/TFCP2L1/UBP1 has been found to act as a TF in cancer." (PMID 32391054, 2020). "With respect to the immune system, RFX1 acts as an activator of MHC Class II genes and represses MCP1, CD11a, CD70, IL17A, TLR4, and the TGFβ2 expressions, which could be instrumental in understanding etiology and materializing treatment strategies for cancer and other immune-related disorders." (PMID 33964962, 2021).
cancer (continued). "In addition, the lack of evidence for a field effect for most of the studied DNA regions, including for regions with frequent hypermethylation in the cancer tissue (e.g., RFX1 and EN1), is consistent with a field effect rather than contamination of adjacent samples with tumor tissue." (PMID 26510686, 2015).
tumor (16 papers, 2004 to 2025). "We next assessed the association between RFX1 expression and components of the tumor microenvironment, focusing specifically on stromal and immune infiltration." (PMID 41425715, 2025). "By combining RFX1 expression with persistent tumor mutational burden, we proposed a novel nomogram clinical prediction model and validated its predictive performance, and the correlation between high expression and poor prognosis." (PMID 41425715, 2025). "In addition to regulating cellular events at the transcriptional level leading to progression of the tumor state, epigenetic modifications of RFX1 underlie the maintenance of tumor stem cell inheritance." (PMID 41425715, 2025). "Its anti-tumor efficacy is evident by a conspicuous reduction in RFX1 expression levels observed during the transition from normal epithelial cells to adenocarcinomas, as demonstrated by tissue sample analyses." (PMID 41425715, 2025). "To account for potential confounding factors in the survival analysis, we compared key clinical variables—including age (median cutoff: 68 years), sex, and tumor stage—between the high and low RFX1 expression groups using chi-square tests." (PMID 41425715, 2025). "The results showed that the expression level of RFX1 was relatively low in normal intestinal epithelial cells, but significantly increased in tumor cells (p < 0.0001)." (PMID 41425715, 2025). "RFX1 reduces the expression of multiple genes that are oncogenic or enhance tumour growth, such as c‐Myc, transforming growth factor‐β2 and CD44." (PMID 39636301, 2024). "Our study has shown that regulatory factor X1 (RFX1) is a tumour‐suppressive transcription factor that can downregulate the expression of CD44 and growth factors." (PMID 39636301, 2024). "Previous studies have described both the tumor-suppressive and oncogenic roles of RFX1, which involve the regulation of proliferation, the immune system, stemness, and chemoresistance 27,28." (PMID 37781522, 2023). "MiR-4508 activated fibroblasts to form PMNs in the lung and promoted metastatic tumor growth by depleting its target, RFX1, to trigger the IL17A-p38 MAPK-NF-κB signaling pathway." (PMID 37781522, 2023). "A significant number of genes upregulated in the resistant line 61 birds after infection contain binding sites for transcription factors, including CREBP1, which can act as a tumour suppressor, and RFX1, which is a regulator of MHC Class II genes." (PMID 36422592, 2022). "The shrinking levels of RFX1 expression during the tumorigenic transition of normal epithelia to adenocarcinoma in tissue samples attest to its anti-tumor activity." (PMID 33964962, 2021). "In a nude mouse xenograft model, SC-2001 repressed tumor growth and the expression level of RFX-1 and SHP-1, and LC3-II was significantly increased in tumor cells, indicating SC-2001-induced autophagic cell death." (PMID 24952874, 2014). "Only the positive control cell line exhibited Rfx1 expression, suggesting consistent down-regulation of Rfx1 in the tumor samples." (PMID 21935353, 2011). "Thus, in the complex tumor microenvironment, RFX1 appears to be a potential marker of tumor immune alterations, especially of the inflammatory microenvironment." (PMID 41425715, 2025). "And the pleiotropic nature of RFX1 may shape its multifaceted roles in several key tumor signalling pathways." (PMID 41425715, 2025). "Moreover, the RFX1 high-expression subgroup not only shaped the inflammatory tumor microenvironment, but also correlated significantly with the IC50 of most drugs." (PMID 41425715, 2025). "For in vivo validation, immune-competent mouse models, such as syngeneic tumor models or humanized mice, treated with immune checkpoint inhibitors (e.g., anti-PD-1/PD-L1), will be essential to assess whether RFX1 expression influences therapeutic efficacy." (PMID 41425715, 2025).
tumor (continued). "To test this hypothesis, we integrated transcriptomic, mutational, and pharmacogenomic data to delineate the multifaceted role of RFX1 in tumor progression and therapy response." (PMID 41425715, 2025). "This suggests that RFX1 may influence tumor biology not only through immune modulation but also via classical oncogenic signaling." (PMID 41425715, 2025). "Additionally, integrating ChIP-seq and RNA-seq analyses to systematically identify downstream targets and signaling pathways regulated by RFX1 will provide further insights into its mechanistic role in tumor-immune interactions and immune evasion." (PMID 41425715, 2025). "The role of RFX1 in tumour biology has been supported by multiple lines of evidence." (PMID 39636301, 2024). "To determine whether RFX1 KO in macrophages influenced tumor development, we performed the s.c. tumor xenograft model in CKO mice." (PMID 37733446, 2023). "RFX1, via targeting these abruptly expressed target genes could possess potential tumor suppressor activity." (PMID 33964962, 2021). "Moreover, the expression of RFX1 in HCC tumor tissues correlated with tumor size and Edmonson-Steiner grade." (PMID 33519911, 2020). "SNHG17 promotes tumor-like behavior in HCC cells via miR-3180-3p/RFX1." (PMID 33519911, 2020). "Further studies are required to assess whether Rfx1 has a direct tumor suppressive role in the esophageal epithelium." (PMID 21935353, 2011). "Therefore, RFX1 may contribute to tumor progression by promoting the accumulation of specific somatic mutations and influencing genomic stability." (PMID 41425715, 2025). "The pulmonary RFX1 level negatively correlated with each of the two inflammatory signatures, whereas ACTA2 positively correlated with tumor inflammation." (PMID 37781522, 2023). "SC-2001 boosted RFX1 expression in HCC and induced cellular apoptosis with better anti-tumor activity than Sorafenib, an FDA-approved medication for HCC." (PMID 33964962, 2021). "Similarly, RFX1 was upregulated in HCC tumor tissues as compared to that in the normal tissues; these high levels of RFX1 correlated with increasing tumor size and grade." (PMID 33519911, 2020). "Importantly, Huh7 tumor-bearing nude mice treated with SC-2001 showed downregulation of Mcl-1 and p-STAT3 protein expression and upregulation of SHP-1, LC3II, and RFX-1 protein expression." (PMID 24952874, 2014). "This study identifies RFX-1 as a major mediator of SC-2001-induced autophagy and indicates that RFX-1 may play a tumor suppressor role in HCC." (PMID 24952874, 2014).